DCN (decorin)
Diseases named in the same sentence as DCN in open-access papers (continued):
Sharing a sentence is not in itself a finding about the gene and the disease.
tumor (continued). "This study reveals the possible role of ASPN and DCN in tumor progression and provides evidence that both ASPN and DCN can serve as novel prognostic biomarkers of GC." (PMID 34379688, 2021). "In the present study, we found that DCN alters the E-cadherin–EGFR–ERK axis to inhibit invasion and tumor growth of IBC cells." (PMID 33452400, 2021). "DCN is an important component of the ECM and functions as a tumour suppressor in RCC that can inhibit the proliferation and metastasis of RCC cells." (PMID 34358255, 2021). "Decorin’s biological activity is rather complex as it regulates multiple processes in the ECM and in the tumor cells." (PMID 33924197, 2021). "In OT cohort tumor samples, we found up regulation of ASPN in 26 out of 42 samples (61.9%), while DCN was down regulated in 22 out of 42 samples (52.4%)." (PMID 34379688, 2021). "From each HCC sample, one core from the tumor and one from NAT was selected and immunostaining specific for decorin and SMA was performed." (PMID 32477937, 2020). "Thus, DCN within the tumor environment may act to inhibit escape through VEGFR-specific mechanisms." (PMID 32908231, 2020). "Decorin can activate the MAPK pathway by combining with epidermal growth factor, leading to the expression of downstream p21 genes related to tumor differentiation, invasion depth, hyperplasia and metastasis, and the value of prognosis." (PMID 32786144, 2020). "The levels of eight hub genes expression (FN1, CCND1, CDH2, CXCL12, MET, IRS1, DCN and FMOD) in PTC and para-cancerous non-tumor tissues were detected by qRT-PCR." (PMID 32714651, 2020). "Decorin suppressed squamous cell carcinoma in vitro by binding to EGFR to regulate downstream signaling pathways, while it also inhibited tumor formation and metastasis in a xenograft model." (PMID 33202923, 2020). "Decorin is known to bind to EGFR and to activate the MAPK pathway, resulting in the induction of cyclin-dependent kinase inhibitor p21 and suppression of tumor growth." (PMID 32847060, 2020). "Decorin signaling suppressed tumor growth by stimulating PDCD4, shifting the immune response toward a proinflammatory phenotype in a tumor xenograft model." (PMID 32825245, 2020). "The collagen family (COL1A2, COL1A1, COL6A3, and COL5A1), DCN, FBLN1, and POSTN were the most abundant components of the tumor ECM." (PMID 33613617, 2020). "It has been reported that DPT competes with decorin for its interaction with TGF-β 3, which regulates a range of pathological processes, including tumor progression, growth and survival." (PMID 33033513, 2020). "Edwards, in 2012, discussed that in PC, decorin, which also interacts with TGF-b, and betaglycan inhibit tumor growth and metastasis, while versican and perlecan respectively promote cell motility and invasion, and tumor cell growth and angiogenesis." (PMID 32847060, 2020). "In line with that, grade III metastases contained less decorin than those of grade III tumors when measuring its absolute level, as well as its relative level compared to the primary tumor." (PMID 32824864, 2020). "Tumor samples contained significantly less decorin and SMA than that of NAT (p < 0.05 for SMA and p < 0.001 for decorin)." (PMID 32477937, 2020). "DCN expression positively correlated with VEGFR1 & 2 expression and localized to similar areas of tumor." (PMID 32908231, 2020). "In their studies, MMP8 cleaved decorin, which inhibits TGF-β1: The subsequent downregulation of miR-21 expression led to activation of known tumor suppressors such as programmed cell death 4 (PDCD4)." (PMID 31514474, 2019). "RdB/IL12/DCN-treated groups exhibited significantly higher IFN-γ and TNF-α than groups treated with PBS, RdB, RdB/IL12, or RdB/DCN (P < 0.001), suggesting that RdB/IL12/DCN induced a potent tumor-specific adaptive immune response." (PMID 28002796, 2017).
tumor (continued). "A reduction was observed in viable tumor cells along with extensive necrotic regions in tumors treated with RdB/IL12 or RdB/IL12/DCN compared with tumors treated with PBS, RdB, or RdB/DCN." (PMID 28002796, 2017). "Thus, owing to this multifunctionality, DCN may exert its anticancer effects through multiple molecular approaches that all contribute to varying degree to its biological effects on cancer cells and tumor environment." (PMID 26697491, 2015). "We also assessed the effect of OKN-007 regarding the immunoexpression of tumor signaling molecules such as PDGFRα, SULF2, and decorin in the IC-3752GBM pGBM model." (PMID 26248280, 2015). "Administration of decorin antagonized multiple receptor tyrosine kinases (e.g., Met), subsequently leading to the down-regulation of MMP-9 in the context of tumor angiogenesis." (PMID 25781946, 2015). "Decorin, a small leucine-rich proteoglycan in the ECM, is a signaling ligand and native anti-tumor agent." (PMID 26379028, 2015). "Decorin's binding to EGFR initially leads to receptor's prolonged activation, followed by EGFR internalization and degradation, eliminating tumor growth and metastases." (PMID 25140302, 2014). "Decorin, a small leucine-rich proteoglycan of the ECM, is found in the tumour microenvironment and affects the biology of various types of cancer." (PMID 24142880, 2013). "We show that decorin overexpression in the MB49/MB49-I model is required for efficient progression, by promoting angiogenesis and tumour cell invasiveness." (PMID 24142880, 2013). "These analyses identified decorin (DCN) and endoplasmin (HSP90B1) which play important roles regulating the tumour microenvironment and in pathways related to tumorigenesis." (PMID 22363530, 2012). "We validated and quantified this result with fluorescence immunohistochemistry and found that decorin deposition in tumors grown in SPARC−/− mice was significantly reduced, not only within tumors, but at the tumor capsule (p = 0.0051)." (PMID 22348081, 2012). "On the other hand, lumican (and decorin) can be degraded by MMP-14, abrogating the anti-tumour effect of these proteins." (PMID 23236386, 2012). "Importantly, we have reported that decorin severely inhibits Myc function through targeted proteasomal degradation which, in turn, could have stern consequences for the tumor stroma as a favorably pro-tumorigenic environment as Myc is required for the expression of stromal genes." (PMID 23029096, 2012). "The imprinted gene decorin and the oncogene EGFR were down-regulated in tumor tissues, while the oncogene cyclin D1 was up-regulated." (PMID 20092659, 2010). "Of these genes, the imprinted gene decorin and the oncogene EGFR were down-regulated in tumor tissues as compared to normal mammary gland tissues, and the oncogene cyclin D1 was up-regulated in tumor tissues." (PMID 20092659, 2010). "As reported, FN, laminin, collagen-IV and -I, decorin, tenascin and vitronectin are ECM proteins produced and secreted by cells of malignant tumours of glial origin in vitro and in vivo." (PMID 14647148, 2003). "We further explored the topographical and cellular localisation of DCN in the tumour microenvironment in resected tumours, which was not related to the serum levels." (PMID 41392017, 2026). "Decorin was one of those ECM proteins, which is also known to be a tumor suppressor in CRC." (PMID 40617497, 2025). "DCN as a therapeutic gene promotes the degradation of extracellular matrix (ECM) and attenuates transforming growth factor (TGF)-β-mediated immunosuppression to elevate CD4+ and CD8 T+ cells and simultaneously attenuate Treg accumulation in tumor tissues." (PMID 40335925, 2025). "Also, we identified novel predicted tumor-suppressive ligands (SLIT3, DCN, CCN3, THBS1, INHA and INHBA), proteins (DNASE1L3, SULF1, PTEN, OAS1, and DAB2IP), and receptors (P2RX4, CDHR2, PTPRJ, and PTPRH) in MSC1 cells." (PMID 40564222, 2025).
tumor (continued). "In this study, DCN was found to be absent to low in the small stromal septa near tumor cell nests, especially in MetB cases." (PMID 40841830, 2025). "Their work revealed that SPP1-mediated ECM remodeling promotes collagen VI (COL6A3) and decorin (DCN) deposition, creating a fibrotic tumor microenvironment that physically excludes cytotoxic T lymphocytes (CTLs) and contributes to immune evasion." (PMID 41293726, 2025). "In addition, decorin negatively regulates insulin-like growth factor receptor I (IGF-IR) and hepatocyte growth factor receptor (Met) and can inhibit tumour cell growth and migration." (PMID 41300368, 2025). "Similarly, PSA score correlated with SDF1 and DCN, and inversely with ERG + endothelium, while tumor Ki67 correlated with SMA and ERG + endothelium." (PMID 40841830, 2025). "Furthermore, DCN is underexpressed in tumor tissues of HCC patients, and overexpression of DCN can inhibit the proliferation of HCC cells, while knockdown of DCN can enhance HCC cell proliferation, making it a new target for HCC." (PMID 40051627, 2025). "Decorin (DCN) and lumican (LUM), which are involved in the regulation of COL fibril assembly and stability, had high abundances in both NAT and tumor tissues; but their levels were much higher in NAT tissue than in tumor tissue." (PMID 40032993, 2025). "FR exhibited a high level of basement membrane proteins and fibroblast lineage markers (COL4A1, FBLN5, DCN, DPT) and is enriched for ECM organization, wound-healing, and cell adhension pathways, suggesting a potential shared mechanism between tumor-surrounding stroma and tissue repair." (PMID 39870619, 2025). "Unlike versican, which consistently promotes tumor progression, decorin appears to have a more multifaceted role in cSCC." (PMID 38730679, 2024). "Decorin (DCN), a leucine-rich small-molecule proteoglycan in the extracellular matrix (ECM), regulates a variety of cellular processes including collagen fibrillogenesis, wound repair, vascular arrest, tumor growth, and autophagy." (PMID 39258145, 2024). "Quantitative PCR analysis of tumor tissues demonstrated that rAd.DCN + NK combination treatment significantly upregulated perforin and IFN-γ expression and downregulated HIF-1α expression compared to rAd.DCN or NK monotherapy groups." (PMID 39482550, 2024). "Furthermore, in order to determine the expression levels of Decorin, IL-2, and IFN-γ in tumor tissue, a qPCR assay was conducted." (PMID 39482550, 2024). "Indeed, a number of proteins within the PG score, such as LUM, HSPG2, DCN and BGN, have established tumor suppression functions in other cancer types." (PMID 38810090, 2024). "Importantly, the overexpression of NCL and NCAM and the downregulation of DCN and LUM in the NB patient-derived exosomes compared to the CTRL samples was confirmed also in primary tumor tissues." (PMID 37947594, 2023). "We have defined the top 5 marker genes (ADH1B, CFD (DF), SEPP1 (SELENOP), DCN, and A2M) that could be used for the identification of ADH1B+ CAFs in tumor tissues." (PMID 37848457, 2023). "No tumour-related deaths occurred in 18 dogs with a low VEGF/type 3 decorin combination, compared to 6/12 (50%) deaths in STS with a high VEGF/type 1 decorin combination (log rank 16.7, p = 0.005)." (PMID 37104411, 2023). "The decorin immunostaining pattern was significantly correlated with the histological grade of the STS with low-grade tumours more likely to have a type 3 pattern and high-grade tumours more frequently having a type 1 pattern (p < 0.001)." (PMID 37104411, 2023). "Moreover, the expression of DCN and TLR2 was decreased in CRC tissue compared with their adjacent non-tumor tissue, and the abundance of B.adolescentis was positively correlated with the expression of TLR2 and DCN in CRC tissue." (PMID 37464382, 2023). "dcn significantly inhibited tumor progression, decreased bone destruction and prolonged survival relative to the virus control without decorin (Ad.luc)." (PMID 35155581, 2022).
tumor (continued). "Furthermore, an oncolytic adenovirus co-expressing DCN and a soluble Wnt decoy receptor markedly prevents EMT and cancer cell metastasis in an orthotopic pancreatic xenograft tumor model." (PMID 36358747, 2022). "Though cigarette smoke exposure-reduced DCN was found to be negative prognostic factor in KIRC, increasing evidences indicate that lack of DCN expression has been regarded as an indicator of tumor metastasis." (PMID 35140327, 2022). "Using qPCR, we analysed the expression of DCN, miR-200c and five lncRNAs (LUCAT1, MALAT1, lncTCF7, XIST, and ZFAS1) in lymph node and liver metastases in comparison to the invasive front and central part of a primary tumour." (PMID 35052821, 2022). "The increase of APOB expression may promote the interaction between DCN and COL1A1, so as to promote tumor metastasis." (PMID 36428687, 2022). "In the cancer milieu, decorin signals through EGFR and Met receptors found on the surface of cancer cells, effectively resulting in decreased HIF-1α and marked angiostasis of the tumour vasculature, suppression of tumour growth and enhanced mitophagy." (PMID 34982945, 2022). "Moreover, decorin competes with the natural ligand of EGFR, the epidermal growth factor (EGF), and the decorin-EGFR interaction results in internalization and degradation of the receptor via caveolar endocytosis, thus controlling tumor growth." (PMID 34917515, 2021). "The TCGA-STAD cohort, revealed a significantly elevated ASPN gene expression in GC tissues vs matched adjacent non-tumor tissues, while reduced expression of DCN was found in cancer tissues vs normal non-tumor tissues." (PMID 34379688, 2021). "Although these results suggest that DCN may act as a tumor suppressor in IBC, the functional role of DCN in IBC tumor aggressiveness and metastasis is unknown." (PMID 33452400, 2021). "The PPI network also reveals that proteins were related with cell adhesion of the ECM remodeling pathway (DCN, FN1 etc.), suggesting that VCAN may be involved in tumor progression which is an important ECM component through the ECM remodeling pathway." (PMID 33604385, 2021). "DCN, a well-studied SLRP was predominantly down regulated in tumor samples." (PMID 34379688, 2021). "In contrast to the in silico results, neither the relative amount of decorin mRNA, nor its protein level was downregulated in tumor samples compared to normal tissue." (PMID 32477937, 2020). "Upon TA-induced hepatocarcinogenesis, the highest tumor count was observed in mice with no decorin production." (PMID 32477937, 2020). "Moreover, COL6A3, DCN, and LUM, which were upregulated after the WNT pulse here, are all typical markers for the switch to a mesenchymal phenotype in lens epithelial and tumor cells." (PMID 33195222, 2020). "In contrast, a high number of α-SMA-positive activated HSCs were detected in the tumor stroma, but there was hardly any, or negative decorin expression in the same sample." (PMID 32477937, 2020). "Collagen VI, DCN, and MMP14 are also functional players in the tumor microenvironment." (PMID 33317052, 2020). "This might be explained by possibly different cellular effects of decorin and biglycan via TLR signaling found for example in tumor cells, where opposite effects of these proteoglycans on tumor growth via TLR have been shown." (PMID 32731559, 2020). "Biglycan is a small leucine-rich proteoglycan that, unlike decorin and endorepellin, promotes neovascularization in the tumor microenvironment." (PMID 33020183, 2020). "According to the Human Protein Atlas database, decorin level is significantly reduced in various tumor types compared to their non-tumorous tissue pair." (PMID 32477937, 2020). "Additionally, IRS1 (insulin receptor substrate 1), DCN (decorin), FMOD (fibromodulin), and CXCL12 (chemokine C-X-C motif ligand 12) were down-regulated in tumor tissues." (PMID 32714651, 2020).
tumor (continued). "Köninger and coworker demonstrated that decorin is mostly released by PSC rather than by tumor cells in PC; however, cancer cells are sensitive to the decorin-dependent anti-tumor activity of chemotherapeutic drug carboplatin." (PMID 32012917, 2020). "Upon thioacetamide exposure the highest tumor number was observed in animals with no excessive decorin production." (PMID 32477937, 2020). "Ectopic expression of DCN and SORBS1 inhibited HepG2 cell growth and colony formation in 2-D plates respectively, validating their tumor suppressor function." (PMID 31903133, 2020). "Our previous studies showed that the lack of decorin favors primary hepatocarcinogenesis resulting in higher tumor incidence." (PMID 32477937, 2020). "Studies on mice with ablated decorin genes revealed that the lack of decorin is permissive for tumor development." (PMID 32824864, 2020). "And the destruction of the decorin will not lead to the spontaneous development of the tumor, but the absence of the decorin will allow the tumor to form." (PMID 32596162, 2020). "miR-484 is a tumor suppressor miRNA between MEG3 and Decorin in our module." (PMID 31182759, 2019). "Specifically, higher decorin expression in the tumor stroma in node-negative invasive breast cancer is correlated to better prognosis due to the modulation of the EGF family of tyrosine kinase receptors downstream signaling." (PMID 29559954, 2018). "At the same time, tumor-suppressive genes such as MT1G, MT1M, CDKN1C, and DCN were overexpressed." (PMID 30568916, 2018). "Moreover, decorin restrains angiogenesis by binding to thrombospondin-1, TGFβ, VEGFR-2, and possibly IGF-IR, and then halting tumor growth by antagonizing oncogenic TKRs and angiogenesis." (PMID 28789706, 2017). "The MBC tumour was shown to be completely negative for decorin immunoreactivity demonstrating that the malignant cells were not able to synthesize decorin." (PMID 28653173, 2017). "Next we showed that the tumour was completely negative for decorin immunoreactivity indicating that the cells that formed the MBC tumour were not able to synthesize decorin, a well-known oncosuppressive PG." (PMID 28653173, 2017). "The results demonstrated that the tumour tissue was completely negative for DCN immunoreactivity, while BGN immunoreactivity was locally clearly detected." (PMID 28653173, 2017). "Furthermore, tumor tissue treated with RdB/IL12/DCN showed increases infiltration of CD8+ T cells and proficient viral spreading within tumor tissues." (PMID 28002796, 2017). "Moreover, RdB/IL12/DCN attenuated intratumoral TGF-β expression, which positively correlated with reduction of Treg cells in draining lymph nodes and tumor tissues." (PMID 28002796, 2017). "Next we examined the immunoreactivity for two stromal PGs, namely DCN and BGN, in this MBC tumour." (PMID 28653173, 2017). "In addition, decorin has been reported to be able to reduce the expression of VEGF at the mRNA and protein level and decrease angiogenesis in tumor cells." (PMID 28290552, 2017). "Collectively, these results demonstrated that an oncolytic Ad co-expressing IL-12 and DCN alleviated TGF-β-mediated immunosuppression and reduced infiltration of immunosuppressive Treg cells in tumor microenvironments, facilitating IL-12-mediated T cell antitumor immunity." (PMID 28002796, 2017). "Studies on DCN knockout mice have established that a lack of DCN is permissive for tumor development and it is regarded as a tumor suppressor gene." (PMID 26697491, 2015). "However, when tumor cells became resistant to metformin after long-term and high-dose inducement by metformin, MMP7 and DCN expression was restored again, implying that the dosage of metformin should be limited in a low level." (PMID 25909163, 2015).